SP100 (SP100 nuclear body protein)
Diseases named in the same sentence as SP100 in open-access papers (continued):
Sharing a sentence is not in itself a finding about the gene and the disease.
cancer (continued). "Even though the positioning patterns of SP100 and TGFB3 are inferior to the Gleason system at stratifying cancers, our results reveal subtype-specific genome organization." (PMID 31681438, 2019). "In keeping with previous studies, we find similar positioning patterns for both SP100 and TGFB3 amongst normal tissues and between normal and benign disease tissues, highlighting that the gene repositioning in cancer tissues were specific to cancer." (PMID 31681438, 2019). "Consistent with Gleason score, the direction that SATB1 and LMNA repositioned did not aid in stratifying cancers by Gleason grade, but the direction of repositioning did correlate with Gleason grade for SP100 and TGFB3." (PMID 31681438, 2019). "No gene is found down-regulated in all three cancer subtypes at once: SP100 loses expression in LS-CRC and MSS s-CRC, while RAD52 deactivates in MSS and MSI s-CRC." (PMID 31750255, 2019). "SP100, TGFB3 and MMP9 each map to different chromosomes (HSA 2, 14 and 20, respectively) and therefore represent independent repositioning events within the subgroups of different Gleason score cancers." (PMID 31681438, 2019). "The proportion of cancers in which SP100 and TGFB3 repositioned also did not stratify Gleason score groups." (PMID 31681438, 2019). "While three of the chimeras (ACTB->POTEM, ACTB->POTEE and SP100->HMGB1) have been found in normal population, three of the chimeras (C2orf27A->NBEA, HILPDA->EFCAB3, FARSB->TRIM61) were previously identified only in cancer samples." (PMID 25133550, 2014). "For six of these cancers SP100 was repositioned but TGFB3 was not, whereas in three cancers only TGFB3 was repositioned." (PMID 31681438, 2019). "However, SP100 and TGFB3 were repositioned in a similar proportion of low Gleason score cancers with or without metastasis." (PMID 31681438, 2019). "The repositioning patterns of SP100 and TGFB3 could not distinguish intermediate from high Gleason score cancers." (PMID 31681438, 2019). "The positioning patterns of SP100 and TGFB3 could not distinguish intermediate Gleason score cancer tissues from high Gleason score cancer tissues." (PMID 31681438, 2019). "Thus, in addition to the high false negative rate for Gleason score, SP100 and TGFB3 can not distinguish aggressive low Gleason score cancers from non-aggressive low Gleason score cancers, limiting their clinical potential." (PMID 31681438, 2019). "Positioning patterns for SP100 and SATB1 were similar in low and high T stage cancer specimens and could not be used to distinguish the different T stage group cancers from each other." (PMID 31681438, 2019).
overlap syndrome (5 papers, 2021 to 2025). "These subtypes exhibit distinct serological profiles, with AMA-negative cases often presenting PBC-specific antinuclear antibodies (anti-gp210, anti-sp100) and overlap syndromes demonstrating combined autoantibody patterns characteristic of both conditions." (PMID 41375805, 2025). "In fact, MND, differentiated by anti-sp100, can also be found in other diseases, e.g., rheumatological and other connective tissue disorders, while anti-sp100 is much more specific for PBC." (PMID 33507492, 2021). "The distribution of each autoantibody by IB among two patients with overlap syndrome was PML which was positive only in the first patient, and Sp100 was positive in the second patient." (PMID 36422475, 2022). "Antibodies prevalent in PBC (AMA-M2, AMA-M2-3E, sp-100, gp-210, anti-Ro52) were also seen in some cases of AIH, though they did not fulfill the criteria of the overlap syndrome." (PMID 34820249, 2021).
infectious disease (1 paper, 2018). A disorder directly resulting from the presence and activity of a microbial, viral, or parasitic agent in humans. "It has been shown that Sp100 interacts viral genomes to suppress infectious disease processes." (PMID 35558957, 2018).
SP100 also shares sentences with these, for which no sentence is quoted: autoimmune hepatitis (3 papers); glioblastoma (2); lupus (2); rheumatoid arthritis (2); Autoimmunity (1); chronic leukemia (1); clear cell renal cell carcinoma (1); diabetes (1); dyslipidemia (1); gastric cancer (1); heart failure (1); lupus nephritis (1); mantle cell lymphoma (1); myositis (1); oral squamous cell carcinoma (1); osteosarcoma (1); pancreatic cancer (1); primary Sjögren's syndrome (1); sarcoma (1); Stroke (1); vasculitis (1).